TNC (tenascin C)
Diseases named in the same sentence as TNC in open-access papers (continued):
Sharing a sentence is not in itself a finding about the gene and the disease.
tumor (continued). "We decided to formally examine this hypothesis and determined that growth on the tumor-associated matrices collagen I and tenascin C impaired the ability of TSP-1 and IP-10 to inhibit endothelial cell proliferation and induce endothelial cell apoptosis (in the case of collagen I)." (PMID 16262896, 2005). "A confounding factor is the immunosuppressive tumor microenvironment determined by tenascin-C (TNC), a highly abundant extracellular matrix molecule upregulated by IR." (PMID 41917325, 2026). "Tenascin-C (Tn-C), an ECM glycoprotein associated with tissue repair, inflammation, and even tumour progression, was found to be significantly upregulated after multiple PDT sessions." (PMID 39859342, 2025). "Several antibodies have been generated against different domains of TNC and shown to efficiently localize to tumor tissue." (PMID 40944718, 2025). "In contrast, TNC was specifically overexpressed in malignantcell populations, particularly in tumor cells with mesenchymal-like(MES-), astrocyte cell-like (AC−) and oligodendrocyte progenitorcell-like (OPC−) subtypes." (PMID 40056466, 2025). "In HNSCC, intense staining of tenascin C is observed in the tumour stroma, with pronounced immunoreactivity frequently surrounding advancing tumour cell islets." (PMID 41009413, 2025). "The Notch2/RBPJk pathway has been identified as a direct regulator of TNC in specific tumor contexts." (PMID 40981103, 2025). "In paired analysis, glioblastomapatients exhibited a 3.9-folddecrease of TNC+/CD9+ EVs after tumor removal(p < 0.001)." (PMID 40056466, 2025). "These cells interact with their microenvironment, which results in the increased accumulation of hyaluronic acid (HA) and tenascin-C (TNC), facilitating tumor migration." (PMID 41294817, 2025). "Tenascin-C-targeting imaging using 124I-F16SIP demonstrated selective tumor localization and good tolerability." (PMID 41211421, 2025). "To favor the tumor infiltration by cytotoxic effector T cells, we generated CARs targeting TNC, an extracellular matrix protein abundantly expressed in the tumor microenvironment of both hematologic and solid cancers." (PMID 40944718, 2025). "Tenascin-C (TNC) promotes tumor progression through multiple mechanisms within the tumor microenvironment." (PMID 41174721, 2025). "Additional context-dependent markers include CD90 (Thy-1), podoplanin (PDPN), and tenascin-C (TNC), which are associated with immune modulation, stromal remodeling, and therapy response in specific tumor types." (PMID 41441395, 2025). "Tenascin-C in tumor derived exosomes in metastatic pancreatic cancer attenuates collagen gel mediated tumor cell apoptosis through the TGF-β pathway in non-cancerous stellate cells." (PMID 41347080, 2025). "High PLAT expression was significantly associated with a poor tumor prognosis, and PLAT was also coexpressed with ITGB3 and TNC." (PMID 39754146, 2025). "In this regard, it has been reported that tumor EVs containing tenascin C induce Wnt/β-catenin signaling, EMT, and tumor progression." (PMID 41515889, 2025). "In this sense, the substantial increase in COL1A1 and other ECM remodelling-related genes, such as MMP9 and TNC, after IL-36γ stimulation in HT- 29 cells underscores the role of this cytokine in modulating the tumour microenvironment." (PMID 40268791, 2025). "In contrast, GLYs, such as the fibrinogen family (FGA, FGB, and FGG), fibronectin (FN1), transforming growth factor beta-induced protein (TGFβI), and tenascin-C (TNC), had an increased presence in tumor tissues." (PMID 40032993, 2025). "In different cellular contexts, such as fibroblasts and tumor cells, TNC exerts a marked anti-adhesive effect by interfering with fibronectin (FN)-mediated adhesion signaling." (PMID 40981103, 2025). "Of particular interest was the altered phosphorylation of TNC (Tenascin C), which plays a crucial role in tumor microenvironment modulation and metastatic progression." (PMID 40861812, 2025).
tumor (continued). "TNC expression in cancer has been proposed to promote invasion and metastasis and is commonly thought to be derived from the tumor stroma." (PMID 39951495, 2025). "Changes in phosphorylation states of proteins such as TNC further implicate post-translational modifications in functional regulation during tumor progression." (PMID 40861812, 2025). "Among other things, tenascin-C is responsible for stimulating aggressive growth in many types of tumours." (PMID 41009413, 2025). "TNC is not only overexpressed in tumor tissue, enhancing the localization of CAR-TNC modified CIK cells to the tumor, but is also involved in tissue remodeling and metastasis." (PMID 40944718, 2025). "Recently, tenascin-C was reported as a critical matrix molecule that impairs CD8+ tumor-infiltrating lymphocyte motility in a CXCL12-dependent manner." (PMID 40977682, 2025). "Consistent with analyses in other tumour types, we identified Tenascin-C in high abundance and upregulated in HR-M3 pUM." (PMID 39500968, 2024). "E-cadherin was restricted to the epithelial compartment whereas collagen-1 and tenascin-C revealed the stromal compartment of the tumor as observed by both IMC and IHC." (PMID 38803925, 2024). "Fibroblasts and normally activated fibroblasts express factors and ECM proteins implicated in tumor cell dormancy, while most CAFs express factors and ECM proteins, such as tenascin C, which are generally implicated in tumor cell reactivation." (PMID 39682261, 2024). "The top 20 targets highly upregulated in tumor compared to all NT (ranked according to the log2(FC) T vs CT) include transcripts encoding for COL11A1, TNC, PTK7, and P4HA3." (PMID 39681068, 2024). "Inhibiting TNC expression by tumor cells reduces proliferation and can reverse the mesenchymal phenotype to epithelial cells." (PMID 38660622, 2024). "IMC analysis also revealed indications for Tenascin-C as a potential target for tumour-core-specific drug resistance and high-dose doxorubicin resistance following its significantly increased prominence in 20 μM Dox models." (PMID 38921450, 2024). "Tumor-derived Tenascin-C facilitates immunosuppression and promotes pro-tumor (M2) macrophage phenotype via activation of macrophage toll-like receptor-4 (TLR-4) through the binding of the TNC protein C-terminal Fibrinogen-like globe (FBG) domain." (PMID 39660126, 2024). "Our findings demonstrate that ZNF750 and TNC modulate tumor proliferation, invasion, metastasis, and immunogenicity." (PMID 38711034, 2024). "The inhibition of TNC by knockdown can inhibit cancer cell proliferation, migration, and invasion and suppress tumor growth in vivo." (PMID 39273015, 2024). "The glycoprotein tenascin-C (TNC) is an ECM-related component highly expressed in tumor stroma and plays a comprehensive role in cancer." (PMID 39403603, 2024). "Here, tumor sEVs containing tenascin-C (TNC) were reported to induce Wnt/β-catenin signaling, EMT, and tumor progression." (PMID 38339318, 2024). "TNC is highly expressed in tumor cells and acts in a variety of ways by binding to integrin receptors." (PMID 37692522, 2024). "Vascular invasions are described as clusters of proliferating epithelial tumor cells enveloped by a luminal endothelial cell monolayer and by Fsp1-positive fibroblasts containing FN, laminin and TNC between the two stromal cell layers." (PMID 38660622, 2024). "TNC promotes tumor progression in several ways (e.g., metastasis and decreased immune response), and knock-down (KD) of TNC impaired BC metastasis and colonization to lungs and bone." (PMID 39696035, 2024). "ZNF750 regulates TNC expression and affects the proliferation, invasion, migration and immunogenicity of cells in vitro, as well as tumor growth in vivo." (PMID 38711034, 2024). "Consistent with its in vitro functional role, clinicopathological analysis of LUSC revealed low expression of ZNF750 in tumor tissue juxtaposed with high expression of TNC." (PMID 38711034, 2024).
tumor (continued). "TNC is an extracellular matrix glycoprotein known to contribute to tumor progression, and increased TNC expression in LUAD tissues correlates with an unfavorable clinical outcome for patients." (PMID 39267750, 2024). "Downregulation of tenascin C significantly impaired the ability of cancer cells to disseminate and colonize the lungs and reduced tumor relapse." (PMID 39682261, 2024). "TNC gene is involved in cancer and has been found to play various roles in tumorigenesis and tumor progression." (PMID 37759229, 2023). "We previously showed that, following MET activation, Capan-I cells upregulate Tenascin C secretion and that this molecule promotes the stroma rewiring needed to fully support both primary tumor growth and cancer cell dissemination." (PMID 37345079, 2023). "Tenascin C has also been shown to promote tumor progression in a carcinogen-induced immunocompetent mouse model of OSCC by stimulating the formation of an immunosuppressive stroma." (PMID 38003931, 2023). "Generally speaking, the role of TNC in cancer includes cell proliferation, differentiation or migration, as well as the upregulation of pro-inflammatory and tumor-promoting cytokines due to activation of toll-like receptor-4 (TLR4)." (PMID 37834140, 2023). "CAFs also secrete a series of factors and proteins, such as CXCL12 and Tenascin C, which promote tumor metastasis and densify the tumor matrix to build a barrier to prevent drug penetration." (PMID 36762192, 2023). "TNC was abundantly expressed in patient metastases and widely expressed across diverse metastatic sites originating from several primary tumor types." (PMID 37098922, 2023). "Tumor cell entry into the lung was also promoted by TNC through epithelial-mesenchymal transition (EMT) involving platelets and transforming growth factor β (TGFβ) signaling." (PMID 36102918, 2022). "The TNC gene was evaluated in tumor tissues and primary cultures of patients with GBM, and its increased expression was associated with the process of carcinogenesis and invasion." (PMID 35992881, 2022). "We also describe the functional role of key proteins, especially tenascin C and fibronectin, and signaling molecules involved in the formation of the tumor microenvironment, as well as the signaling pathways that they activate in cancer cells." (PMID 35008401, 2022). "Advances using murine models with engineered TNC levels were instrumental in the discovery of important functions of TNC as a danger-associated molecular pattern (DAMP) molecule in tissue repair and revealed multiple TNC actions in tumor progression." (PMID 36102918, 2022). "A similar tumour-promoting effect can be assigned to activation of the gene for ECM protein tenascin-C." (PMID 34837514, 2022). "In iCCA, TnC is selectively expressed by the tumor invasion front, and its expression correlates with adverse outcomes." (PMID 39301518, 2022). "TNC has also been proposed to promote tumor progression by inducing integrin α5β1-mediated YAP activation and upregulating metastasis-associated lung adenocarcinoma transcript 1 (MALAT1) in Ewings sarcoma." (PMID 36102918, 2022). "With the recent advent of novel tumor models, comprehensive omics and pathway analysis, as well as novel targeting tools, we have gained significant insight into TNC as a critical regulator of tumor immunity." (PMID 36102918, 2022). "CSC partly reduces AKT and ERK signal transduction by releasing related extracellular vesicles or free tenascin C (TNC) to escape from anti-tumor T cells but induce tumor-promoting regulatory Tregs." (PMID 35222443, 2022). "Like fibronectin, tenascin-C was also detected in extracellular vesicles released into the extracellular space by most cell types, including fibroblasts and tumor cells." (PMID 35008401, 2022). "Experiments in vivo showed that knockdown of tenascin-C inhibited tumor growth and peritoneal dissemination and suggested the involvement of tenascin-C in vasculogenic mimicry formation." (PMID 35008401, 2022).
tumor (continued). "The aptamer GBI was released upon interaction with ECM component tenascin-C and exposed the cell-penetrating peptide for tumor cell internalization." (PMID 35154473, 2022). "Tumor cells preferentially invade along aligned fibers and we observed tumor cells populated along Tenascin-C tracks in early human LUAD." (PMID 36279309, 2022). "Expression of tenascin-C in tumor stroma was found in regions called tumor matrix tracks that are composed of several matrix molecules and are enriched with stromal cells including endothelial cells, fibroblasts and immune cells." (PMID 35008401, 2022). "In GBM, the ECM consists of higher levels of collagen, fibronectin, laminin, hyaluronic acid, tenascin-C and vitronectin and the exact composition of any individual tumor varies with the stage of tumor growth as the extracellular matrix becomes more remodeled." (PMID 36276147, 2022). "Various ECM components (hyaluronan, collagen, SPARC, α-SMA, tenascin C), that contribute to fibrosis, are overexpress in activated stromal cells (fibroblasts, myofibroblasts, stellate cells) and, in some cases, in tumor cells." (PMID 35447719, 2022). "Tracks of aligned ECM, including those composed of collagen, fibronectin, and Tenascin-C are a signature of invasive cancer and can serve as a conduit for tumor cell dissemination." (PMID 36279309, 2022). "These PGs are involved in tumor or stem cell adhesion and proliferation by interacting with multiple domains of TNC or peptides derived from TNC." (PMID 36033448, 2022). "Glycosylated tenascin C in EVs from different tumor and non-tumor tissues was successfully used to distinguished them with high specificity and sensitivity." (PMID 36430846, 2022). "IDHmut has been shown to restrict tumor aggression by decreasing HIF1α-dependent tenascin C expression, thereby decreasing ECM stiffness and mechanosignaling." (PMID 36076905, 2022). "As an ECM glycoprotein, TNC has been shown to exert different effects on different cells during tumor proliferation." (PMID 36033448, 2022). "The experiments were done in the context of either TNC knockdown or TLR4i-treated metastases, after primary tumor removal." (PMID 35469015, 2022). "TNC promotes tumor growth by directly influencing intracellular signaling activating tumor proliferation, survival, and epithelial to mesenchymal transition (EMT)." (PMID 35948987, 2022). "Prototypical matrikines involved in epithelial/cutaneous processes such as wound healing or tumor cell invasion include the epidermal growth factor-like repeats (EGF-L) of tenascin-C and laminin/Lng2." (PMID 36230826, 2022). "Tenascin C closely resembles fibronectin and shares receptor-binding properties, promoting proliferation and migration of tumor cells." (PMID 34884982, 2021). "Several mouse models reveal the importance of TnC in tumor progression and its implication in tumor cell survival, proliferation, invasion and metastasis." (PMID 33981316, 2021). "These MSCs produce hepatocyte growth factor (HGF) and tenascin C, which enhances tumor proliferation and promotes transformation into invasive phenotypes." (PMID 34957091, 2021). "In the present work, we examine patterns of tenascin-C expression in the stroma of tumour-free lymph nodes collected from muscle-invasive bladder cancer (MIBC) patients and determine their prognostic significance." (PMID 34564696, 2021). "In ALCL tumor tissues, TNC is strongly and diffusely expressed in stromal cells, vasculature and tumor cells." (PMID 33562105, 2021). "Tenascin C binds the TLR4 to induce activation of tumor-associated macrophages and microglia and patterning towards an M2 phenotype essential for tumor growth and progression." (PMID 33805316, 2021). "Either integrin-α9β1 or TNC antibodies reduce CCL21 mRNA and protein expression to improve hypoimmunity, suggesting that blocking integrin-α9β1 or TNC can alter the SCC tumour microenvironment." (PMID 33790909, 2021).
tumor (continued). "Findings such as the involvement of TNC in tumor growth, metastasis and stemness have rejuvenated the research area of oncology." (PMID 33876384, 2021). "Other studies have proven that TNC has a significant role in tumor growth, migration, metastasis, angiogenesis, and stromal inflammation." (PMID 34320931, 2021). "Rigid ECM stimulates MSCs in the TME to secrete hepatocyte growth factor (HGF) and tenascin C, factors that promote tumor proliferation and transform into invasive phenotypes." (PMID 34957091, 2021). "As with the EMILIN2-PDGFD fusion, it is difficult to determine with certainty if TNC-PDGFD plays a driving role in the transformation of this tumor from DFSP to fibrosarcomatous DFSP, but it is a possible candidate." (PMID 34256767, 2021). "The role played by TNC in MET-mediated tumor-stroma cross-talk has been further investigated by knocking-down TNC expression." (PMID 34298732, 2021). "High tenascin-C expression in primary tumour stroma predicts worse survival in a number of cancers including breast, colorectal, oesophageal squamous cell, and bladder carcinomas." (PMID 34564696, 2021). "elucidate a mechanism involving the cytokine IL-33 and receptor ST2 in the tumor milieu that stimulates expression and accumulation of TNC via NF-κB signaling in the microenvironment." (PMID 35127517, 2021). "The extracellular matrix (ECM) molecule Tenascin-C (TNC) is well-known to promote tumor progression by multiple mechanisms." (PMID 33790905, 2021). "In a recent study, the proteoglycan versican (VCAN) and the glycoprotein tenascin C (TNC) also proved to be able to distinguish tumor from non-tumor tissues with high sensitivity and specificity, pointing to their use as cancer EVs markers." (PMID 33430152, 2021). "TNC, an extracellular matrix protein, plays an important role in tumor cell invasion and metastasis." (PMID 33996555, 2021). "Recent studies demonstrate that exosome secretion is strictly required for appropriate extracellular TnC deposition by both tumor cells and different fibroblast types." (PMID 33981316, 2021). "PL3-coated nanoparticles were accumulated in tenascin-C positive areas in clinical tumor samples suggesting that PL3 peptide can be used as a targeting peptide for selective delivery of therapeutics to the site of solid tumors." (PMID 34833427, 2021). "As part of the AngioMatrix, TnC can participate in the angiogenic switch, and generate an aberrant vasculature within tumours." (PMID 33981316, 2021). "The FHKHKSPALSPVGGG sequence can selectively bind to another component of ECM in tumor cells, called tenascin-C, which is overexpressed in the tumor microenvironment." (PMID 34833427, 2021). "Collectively, our data suggest a mechanism of tumour EV-driven tenascin-C induction in the stroma of MIBC regional lymph nodes." (PMID 34564696, 2021). "Tenascin-C is a large glycoprotein that is upregulated in tumor ECM, and it plays a supportive role in tumor growth, angiogenesis, and metastasis." (PMID 33572559, 2021). "Recently tenascin-C was shown to contribute to the immune-suppressive microenvironment of the tumor stroma through integrin α9β1 inducing CCL21 (in lymphatic endothelial cells) and TLR4 regulating CCR7 (in CD11c+/dendritic cells)." (PMID 33912190, 2021). "Treatment of mice with function blocking anti-tenascin-C antibodies caused TAM to accumulate at the edge of the tumor, compared to higher numbers within the tumor stroma in untreated mice." (PMID 33718177, 2021). "Cav1-dependent regulation of tissue architecture and cell function is relevant for several conditions in which TnC has a prominent role, such as tumor progression or cardiovascular remodeling." (PMID 33981316, 2021). "To investigate how TNC impacts tumor growth, we used the MMTV‐NeuNT (NeuNT) model on a wild‐type (WT) and TNC knockout (KO) background." (PMID 33988305, 2021).